NLRC4 (NLR family CARD domain containing 4)
Diseases named in the same sentence as NLRC4 in open-access papers (continued):
Sharing a sentence is not in itself a finding about the gene and the disease.
glioma (continued). "We used flow cytometry to evaluate post-optimization and the validation of Tim-3/Gal-9 knockdown or overexpression and NLRC4 inflammasome expression in each glioma cell line." (PMID 35216164, 2022). "Based on the in silico results, we conducted an experimental validation and found that Tim-3/Gal-9 and NLRC4 were significantly positively correlated with each other, as well as glioma malignancy." (PMID 35216164, 2022). "In this study, we investigated the molecular connections between Tim-3/Gal-9 and the NLRC4 inflammasome in glioma." (PMID 35216164, 2022). "Here, we observed that Tim-3/Gal-9 expression increased with glioma malignancy and found that Tim-3/Gal-9 regulate NLRC4 inflammasome formation and activation." (PMID 35216164, 2022). "Tim-3 or Gal-9 downregulation significantly decreased NLRC4 and caspase-1 expression in glioma cells." (PMID 35216164, 2022). "We previously verified that NLRC4 inflammasome expression significantly increases with glioma progression." (PMID 35216164, 2022). "We previously reported that the NLRC4 inflammasome occurs in the glioma TME and is related to poor survival." (PMID 35216164, 2022). "In the NLRC4 inflammasome, upregulation is a marker of poor prognosis in gliomas although the role of inflammasomes in tumors continues to evolve." (PMID 34178034, 2021). "We analyzed the protein expression and localization of NLRC4 in glioma tissues from 11 patients by immunohistochemistry." (PMID 31133717, 2019). "Collectively, these data indicate that both NLRC4 and NLRP3 are upregulated in gliomas and suggest that they potentially associated with glioma progression." (PMID 31133717, 2019). "The level of NLRC4 protein was increased in brain tissues, specifically, in astrocytes, from glioma patients." (PMID 31133717, 2019). "Kaplan-Meier survival plots indicated that glioma patients with high NLRC4 expression had a significantly lower overall survival than those with low NLRC4 expression, whereas the expression of NLRP3 did not have a significant association with overall survival." (PMID 31133717, 2019). "Upregulation of NLRC4 in glioma patients contributes to poor prognosis and could serve as a diagnostic marker." (PMID 41291696, 2025). "Similarly, higher NLRC4 expression is observed in glioma tissues, where it plays a role in tumor progression." (PMID 40692785, 2025). "Another recent study suggested that overexpression of the NLRC-4/IPAF inflammasome could serve as a potential therapeutic target and diagnostic marker for gliomas, potentially associated with poor prognosis." (PMID 39712014, 2024). "Hence, NLRC4 should not only be investigated closely in glioma but also for additional molecular links and mechanisms, including non-canonical pathways and molecular signaling pathways." (PMID 37723542, 2023). "In fact, in silico and in vitro validation results regarding the Tim-3/Gal-9 axis and the NLRC4 inflammasome showed a significantly positive correlation according to the WHO glioma grade, and it was found that Tim-3 regulates the expression and activity of the NLRC4 inflammasome." (PMID 37723542, 2023). "In addition, in glioma cells, overexpression of NLRP12 and NLRC4 inflammasome-associated genes and proteins contributed to malignancy and poor prognosis." (PMID 37749707, 2023). "Tim-3/Gal-9 and the NLRC4 inflammasome contribute to glioma progression." (PMID 35216164, 2022). "We measured Tim-3, Gal-9, and NLRC4 expression at each stage of glioma." (PMID 35216164, 2022). "The influences of Tim-3/Gal-9 on the NLRC4 inflammasome may be used in glioma diagnosis and treatment targeting Tim-3/Gal-9 or the chronic inflammatory microenvironment." (PMID 35216164, 2022). "An immunohistochemical examination was performed to establish whether the NLRC4 inflammasome is expressed in glioma tissues." (PMID 35216164, 2022). "This study demonstrated that Tim-3/Gal-9 are correlated with the glioma NLRC4 inflammasome." (PMID 35216164, 2022).
glioma (continued). "We proposed that a Tim-3/Gal-9 blockade could be beneficial in glioma therapy as it would reduce the inflammatory microenvironment by downregulating the NLRC4 inflammasome." (PMID 35216164, 2022). "Hence, Tim-3/Gal-9 and NLRC4 inflammasome co-expression is correlated with glioma progression and occurs mainly in astrocytes." (PMID 35216164, 2022). "Therefore, further studies are needed to explore the preliminary link between NLRC4-mediated IL-1β secretion and tumor progression, potentially positioning the NLRC4-IL-1β pathway as a potential therapeutic target for inhibition of glioma and other cancers." (PMID 34276697, 2021). "Collectively, these results indicate that NLRC4 inflammasome promotes glioma progression." (PMID 31133717, 2019). "Our data suggest that NLRC4 may represent not only a potential therapeutic target for gliomas, but also a biomarker for diagnosis and prognosis in brain cancer." (PMID 31133717, 2019). "Furthermore, hierarchical clustering of data from the Cancer Genome Atlas dataset showed that NLRC4 was highly expressed in gliomas relative to that in a normal healthy group." (PMID 31133717, 2019). "Notably, inflammasomes are generally expressed in myeloid lineage cells, whereas NLRC4 inflammasome expression is observed in astrocytes and microglia of glioma, suggesting that astrocytes might mediate neuroinflammatory responses." (PMID 37723542, 2023). "The nature of the NLRC4 inflammasomes in glioma remains unclear." (PMID 37723542, 2023). "Furthermore, the expression levels of genes encoding NLR proteins (NLRP12, NOD2, NOD1, NLRC4, and NAIP), inflammasome adaptor molecules (PYCARD), and proinflammatory caspases (CASP1, CASP4, and CASP5) were significantly higher in glioma patients than in normal controls." (PMID 31133717, 2019). "Fewer reports of NLRP6 in glioma have been made compared to NLRP3 and NLRC4, but some progress has been made in recent years." (PMID 37723542, 2023). "Pyroptosis-related gene expression, including NLRC4 and NLRP12, has been found to be increased in glioma." (PMID 38002346, 2023). "NLRP6, which shows robust expression in gliomas, also belongs to the NLR family, similar to NLRP3 and NLRC4." (PMID 37723542, 2023). "Activation of NLRC4 and NLRP3 inflammasomes in microglia and astrocytes, as well as the upregulation of IRF3 and IRF7, contribute to the poor prognosis of glioma." (PMID 38002346, 2023). "The expression of pyroptosis-related genes, including NLRC4 and NLRP12, has been found to be increased in glioma." (PMID 38002346, 2023). "As the correlations among Tim-3, Gal-9, NLRC4, and CASP1 were highly positive, we compared the expression levels of each gene in glioma and healthy tissue." (PMID 35216164, 2022). "We also examined the effects of Tim-3/Gal-9 on the NLRP3 inflammasome in glioma cells and showed that the NLRP3 inflammasome was regulated by Tim-3/Gal-9 similarly to the NLRC4 inflammasome." (PMID 35216164, 2022). "Tissue microarray-based immunohistochemistry results showed higher levels of NLRC4 and N-terminal GSDMD in high-grade gliomas, providing conclusive evidence of pyroptosis in gliomas." (PMID 36199426, 2022). "We have observed high HR (greater or equal to 0.5) for NLRC4, CASP1, NLRP12 and MSR1 genes in grade 3 & grade 4 glioma." (PMID 31186453, 2019). "In conclusion, the histological and bioinformatics analyses of tissue samples and TCGA data from glioma patients provide evidence that NLRC4 and NLRP3 inflammasomes are activated in gliomas." (PMID 31133717, 2019). "Despite the study of NLRC4 and NLRP3 inflammasomes in several neurological diseases (Alzheimer’s disease, Parkinson’s disease, stroke, and multiple sclerosis), their roles in gliomas remain undefined." (PMID 31133717, 2019). "To investigate NLRC4 and NLRP3 inflammasomes as potential prognostic markers in glioma patients, we compared NLRP3 or NLRC4 expression with survival using TCGA data." (PMID 31133717, 2019).
glioma (continued). "However, the role of the NLRC4 inflammasome in gliomas remains unclear." (PMID 31133717, 2019). "These PRGs, which are upregulated in gliomas, include caspase-3 and caspase-9, n-terminally truncated gasdermin D (GSDMD), and the inflammasome proteins NLRP2 (“NLR family pyrin domain containing 2”) and NLRC4 (“NLR family CARD domain containing 4”)." (PMID 39062119, 2024). "Nevertheless, we did not apply either of these to elucidate the glioma TME window or the effects of Tim-3/Gal-9 on the NLRC4 inflammasome." (PMID 35216164, 2022). "Moreover, the NLRC4 and NLRP3 inflammasomes were also found to play a role in glioma that is a tumor of the central nervous system." (PMID 31892810, 2019). "NLRC4 and NLRP3 were detected by immunostaining in the brains of glioma patients." (PMID 31133717, 2019). "Notably, TIM-3/Gal-9 upregulates the expression of NLRC4 and caspase-1 but does not trigger IL-1β secretion in glioma." (PMID 41291696, 2025). "However, the roles of CASP1, NOD1, NLRC4 and NLRP12 are not reported in relation to glioma." (PMID 31186453, 2019).
Obesity (21 papers, 2016 to 2025). Accumulation of substantial excess body fat. "In a novel study, NLRC4 inflammasome has been associated to breast cancer progression in obesity conditions." (PMID 37819510, 2023). "This leads to a NLRC4/IL-1β dependent upregulation of adipocyte derived angiopoietin-like 4 and enhanced obesity associated tumor angiogenesis." (PMID 33339340, 2020). "By using Nlrp3−/−, Nlrc4−/−, Casp1/11−/−, and WT obesity-prone C57BL/6 mice, another study concluded that the NLRC4 inflammasome, associated often with obesity, has a more important role in BC progression than the NLRP3 inflammasome." (PMID 31661891, 2019). "A causal mechanism by which obesity promotes the progression of breast cancer via the NLRC4 inflammasome activation has been recently described but no results showing the impact of NLRP3 in obesity-associated CRC have been reported." (PMID 30619282, 2018). "The authors further show that obesity is associated with NLRC4 inflammasome activation and IL-1β production in myeloid cells, which in turn induces VEGF and angiogenesis." (PMID 28955343, 2017). "Using a fluorescent probe for active CASP1, we also found that obesity-induced CASP1 activation was significantly reduced in CD45+ tumour-infiltrating leukocytes from NLRC4-deficient DIO mice compared with WT DIO mice." (PMID 27708283, 2016). "Currently, it is unclear how obesity is linked to NLRC4 activation in this tumor model." (PMID 28955343, 2017). "As these data suggest that NLRC4 inflammasome/IL-1β drives obesity-associated tumour angiogenesis through a signalling network between macrophages and adipocytes, we stained tumour sections for adipocytes and found a general increase in lipid droplets of tumours from DIO mice compared with ND mice." (PMID 27708283, 2016). "Obesity might aid the progression of cancer through the pathways linked with NLRC4 and VEGFA." (PMID 33167967, 2020). "NLRC4 is an emerging inflammasome that should be evaluated as a possible therapeutic target in the field of obesity." (PMID 40149869, 2025). "Among the several inflammasomes, NLRC4 activation has received relatively little attention in obesity." (PMID 40149869, 2025). "Specifically, NLRC4 mRNA is elevated in normal breast tissues from patients with obesity and positively correlates with BMI." (PMID 37819510, 2023). "The obesity-triggered NLRC4 inflammasome was found to be activated in tumor-infiltrating myeloid cells." (PMID 35836259, 2022). "In two syngeneic orthotopic transplant models, a NLRC4 inflammasome/IL-1β signaling was demonstrated to provide a link between obesity and breast cancer progression." (PMID 33987528, 2021). "We found that tumour-infiltrating CD11b+ cells were the primary source of Nlrc4 in both Py8119 and E0771 tumours, and that obesity further upregulated its expression (open bars)." (PMID 27708283, 2016). "In obesity, increased NLRC4 inflammasome expression links endotoxemia and VAT inflammation." (PMID 40149869, 2025). "Given that HF diet and NLRC4 affect gut permeability and microbiota homeostasis, therefore contributing to endotoxemia and endotoxemia-related inflammation, the investigation of NLRC4 activation in obesity appears to be intriguing as well, but few data are available right now." (PMID 40149869, 2025). "In addition, obesity induces NLRC4/IL-1β-dependent upregulation of angiopoietin-like 4, leading to increased angiogenesis and growth in tumors in mice." (PMID 34944905, 2021). "In addition, obesity leads to an increase in tumor infiltrating macrophages with activated NLRC4 inflammasome and increased IL-1β production in breast tumors." (PMID 33339340, 2020). "In the context of obesity, the tumor microenvironment induces an enhanced level of tumor-infiltrating myeloid cells with an activated NLRC4 inflammasome which further activates IL-1b, thus driving progression of disease through adipocyte-mediated VEGFA expression and angiogenesis." (PMID 33167967, 2020).
Obesity (continued). "Moreover, it has also been reported that obesity-induced NLRC4 inflammasome in tumor-infiltrating myeloid cells promotes angiogenesis in diet-induced obese mice through IL-1β, and that such activation would finally lead to increased Vegfa expression in surrounding adipocytes." (PMID 37819510, 2023).
Sepsis (18 papers, 2019 to 2025). Sepsis is defined as life-threatening organ dysfunction caused by a dysregulated host response to infection. "To explore the upstream targets of PRGs associated with sepsis, we used the NetworkAnalyst online tool to predict the miRNAs of NLRC4." (PMID 36765335, 2023). "We applied machine learning algorithms combined with relevant reviews and databases to screen for PRGs associated with sepsis and ultimately identified NLRC4 as a potentially effective therapeutic target for sepsis." (PMID 36765335, 2023). "Moreover, using a fecal-induced peritonitis (FIP) sepsis model, we found that the NLRC4 deficiency largely protected against lung injury and increased survival rate." (PMID 40158217, 2025). "In this study, we identified NLRC4 as a PRG associated with sepsis based on machine learning and constructed a ceRNA network of lncRNAs and miRNAs around NLRC4, which may serve as early molecular biomarkers for therapeutic targets of sepsis." (PMID 36765335, 2023). "Eventually, NLRC4 was considered the PRG most strongly associated with sepsis." (PMID 36765335, 2023). "Finally, ROC curves were plotted based on the external validation dataset (GSE32707) to verify the potential value of NLRC4 as an early diagnostic marker or therapeutic target for sepsis patients." (PMID 36765335, 2023). "Additionally, NLRC4 has been identified as a diagnostic marker for pediatric sepsis." (PMID 37939116, 2023). "Based on three machine learning algorithms, we screened three potential biomarkers (NLRC4, S100A9 and TXN) and constructed a diagnostic model for sepsis." (PMID 40028203, 2025). "Although we have validated the upregulation of NLRC4, TXN, and S100A9 expression in the peripheral blood of sepsis patients through qRT-PCR, there are still some deficiencies, such as limited number of enrolled patients and the lack of multicenter validation." (PMID 40028203, 2025). "The results of the ROC analysis illustrated the satisfactory diagnostic ability of CHMP7, NLRC4, and PLCG1 for sepsis." (PMID 37939116, 2023). "The study identified seven important PRGs including CHMP7, NLRC4, PLCG1, IRF1, CASP4, NLRP1, GSDMD associated with sepsis." (PMID 37939116, 2023). "The AUC value of NLRC4 was 0.67, which was greater than or equal to 0.65, and it was identified as a sepsis-related key gene." (PMID 36765335, 2023). "During sepsis, NLRC4 activation contributes to pathological and physiological changes, leading to multiple-organ dysfunction." (PMID 37939116, 2023). "The expression level of PLCG1 was continuously significantly decreased, while the expression level of NLRC4 was elevated from control to sepsis and then to septic shock." (PMID 36250055, 2022). "NLRC4 (NLR family CARD domain containing 4) was found to be up-regulated by MAPK pathway in pediatric sepsis, which also inhibited IL‐1β and IL‐18 production to contribute to the anti-inflammatory response." (PMID 33949285, 2021). "It is strongly increased in sepsis, tuberculosis, and after Ebola vaccination as well as in autoinflammatory diseases such as rheumatoid arthritis, NLRC4-MAS, and NOMID, and shows slight overlap with the severe COVID-19 patients in group G1." (PMID 33441124, 2021). "In this study, we found that NLRC4 was upregulated in patient with sepsis." (PMID 40028203, 2025). "NLRC4, as the PRG mostly associated with sepsis, could be considered a potential target for treatment." (PMID 36765335, 2023). "Interestingly, the expression level of PLCG1 was continuously significantly decreased during sepsis development, while the expression level of NLRC4 was gradually significantly elevated." (PMID 36250055, 2022). "Hence, it is plausible to speculate that NLRC4 may induce cell death through caspase-1 activation and enhancement of the inflammatory response, ultimately contributing to the onset of sepsis." (PMID 40028203, 2025).